Y_RNA (Y RNA )
Gene: Miscellaneous RNA gene on chromosome 21 (29,139,283 to 29,139,384, reverse strand). Ensembl gene ENSG00000201984.
Homologues: Orthologues: chimpanzee Y_RNA (98% identical), macaque Y_RNA (95% identical). Paralogues in human: RNY3 (90% identical), Y_RNA (89% identical), Y_RNA (88% identical), RNY3P1 (87% identical), Y_RNA (87% identical), Y_RNA (86% identical), RNY3P16 (85% identical), Y_RNA (85% identical), RNY3P14 (84% identical), Y_RNA (84% identical), RNY3P5 (83% identical), RNY3P7 (83% identical), and 96 more.